TNF (tumor necrosis factor)
Diseases named in the same sentence as TNF in open-access papers (continued):
Sharing a sentence is not in itself a finding about the gene and the disease.
gastric cancer (continued). "In consistent with this report, we found that gastric cancer cell-derived conditioned medium protected neutrophils from spontaneous apoptosis and induced IL-1β and TNFα expression, among other inflammatory factors." (PMID 30292233, 2018). "A recent clinical study on patients with gastric cancer indicated a positive correlation between TNF-α expression and peritoneal metastasis." (PMID 30544870, 2018). "There is a strong association between genetic polymorphisms in the interleukin (IL-)1β and IL-1 receptor gene cluster and in tumor necrosis factor (TNF)-α and the risk of gastric cancer." (PMID 30409143, 2018). "E. The expression of pro-inflammatory factors (IL-1β, IL-6, IL-8, OSM, and TNFα) in gastric cancer cell-derived exosomes-treated neutrophils was determined by qRT-PCR." (PMID 30292233, 2018). "In conclusion, the present study strongly suggests that TNF-α-induced MMP-9 secretions from mesothelial cells play an important role in the metastatic dissemination of gastric cancer." (PMID 30544870, 2018). "Plasma levels of TNF-α in older patients with gastric cancer (≥60 years) were higher than those in young patients (P < .05)." (PMID 29742685, 2018). "Tumor necrosis factor (TNF)-α, a major part in inflammatory, infectious and tumor processes, and is pivotal at the early stages of gastric cancer." (PMID 29867530, 2018). "The transmigration of MKN1 human gastric carcinoma cells through the reconstituted mesothelium was promoted by TNF-α in a dose-dependent manner." (PMID 30544870, 2018). "Circulating concentrations of IL-8 (A and B) and TNF-α (C) in healthy donors and patients with gastric cancer were measured by xMAP." (PMID 28558708, 2017). "In gastric cancer cells, Nrdc has been shown to enhance the ectodomain shedding of TNF-α and subsequent activation of cell cycle-promoting genes, such as Ccnd1 and bcl218." (PMID 29093577, 2017). "In this respect, we previously demonstrated that NRDC regulates activation of TNF-α and subsequent production of inflammatory cytokines in gastric cancer cells." (PMID 28230087, 2017). "We investigated two single nucleotide polymorphisms (SNPs) of TNF-α -1031 and RAF-1 rs1051208- in a gastric cancer in an Iranian population." (PMID 29118938, 2017). "In this context, genes encoding interleukins (e.g., IL-1β), tumor necrosis factor alpha (TNF-α), cyclooxygenase-2 (COX2), and other host factors have been associated with an elevated risk for gastric cancer." (PMID 28398251, 2017). "These previous data showed that TNF-α secreted from gastric cancer cells themselves initiates a feedback loop to enhance inflammatory cytokine expression." (PMID 28230087, 2017). "We previously demonstrated that the deletion of Nrdc critically suppresses ectodomain shedding, activation of TNF-α, and the production of other inflammatory cytokines in gastric cancer cells." (PMID 28230087, 2017). "The reconstitution of TFF1 expression in gastric cancer cells suppressed H. pylori mediated NF-κB activation and expression of cytokine genes (TNF, IL-1β, CCL5, and IL-4 receptor)." (PMID 28350359, 2017). "Helicobacter pylorus, a definitive carcinogen for stomach cancer, is known to induce the expression of pro-inflammatory cytokines such as TNF-α and interleukin-1 in the stomach." (PMID 27556695, 2016). "Significant TNFα elevation in metastatic disease when compared to localized disease has been reported in breast, prostate, pancreatic and gastric cancer patients." (PMID 27713151, 2016). "Tumor necrosis factor plays a critical role in the pathogenesis of gastric diseases such as gastric cancer, and an abnormal inflammatory response has frequently been observed in dyspeptic patients." (PMID 26719751, 2015). "Smad3 was also found to be involved in the transcriptional activation of Bim in human gastric carcinoma cells when simultaneously exposed to both TGFβ and TNFα." (PMID 26405162, 2015).
gastric cancer (continued). "A direct link between the pro-inflammatory effects of TNF-α and carcinogenesis can be seen by returning to the example of gastric cancer." (PMID 24672527, 2014). "The binding complex of nucleolin and Tipα induces expression of TNF-α and chemokine genes and activates NF-κB in gastric cancer cells of humans and mice." (PMID 24469254, 2014). "Serum levels of IL-6 and TNF-α were significantly higher in patients with gastric cancer than gastritis." (PMID 23117246, 2013). "Reduced expression of the OLFM4 gene inhibits cell growth and increases sensitization to hydrogen peroxide and tumor necrosis factor alpha-induced apoptosis in gastric cancer cells." (PMID 23430930, 2013). "The presence of various proinflammatory IL-10 genotypes, TNF-α, IL1B and the IL-1 receptor antagonist increases the risk of development of gastric carcinoma." (PMID 23995914, 2013). "Previous studies showed that lentinan elicited peritoneal macrophages with increased secretion of IL-12 in vitro and reduced IL-10 in vivo and enhanced the production of IL-1β and TNF-α in peripheral monocytes from the patients with gastric carcinoma." (PMID 24223225, 2013). "Blocking OLFM4 expression can sensitize gastric cancer cells to H2O2 or TNF α treatment by increasing caspase-3 dependent apoptosis." (PMID 22471589, 2012). "We previously reported that TGF-ß and TNF-α synergistically induce EMT in serum-free culture of MKN-1 human gastric cancer cells." (PMID 23300891, 2012). "Lycopene treatment had significantly increased blood IL-2, IL-4, IL-10, TNF-α levels and reduced the IL-6 level in gastric cancer rats." (PMID 21686188, 2011). "In this study, blood IL-2, IL-4, IL-10 and TNF-α levels in gastric cancer model control rats were significantly lower than those in normal control rats." (PMID 21686188, 2011). "Compared with the normal control rats, blood IL-2, IL-4, IL-10 and TNF-α levels were significantly reduced in the gastric cancer model rats, while blood IL-6 level was significantly increased." (PMID 21686188, 2011). "The inflammatory response-related host genes that have been most frequently studied in relation to gastric cancer are interleukin (IL) genes and tumor necrosis factor-alpha (TNFA)." (PMID 24212943, 2011). "This study highlights the result that mucosal level of TNF-α mRNA was significantly higher in H. pylori positive patients than that in negative patients by using quantitative real-time PCR, and two gastric cancer cells also secreted TNF-α protein in vitro." (PMID 20699000, 2010). "First, there was a significant upregulation of CXCR4 in gastric cancer cells after they were treated with exogenous TNF-α." (PMID 20699000, 2010). "Our findings demonstrated that H. pylori upregulates CXCR4 expression in gastric cancer through TNF-α." (PMID 20699000, 2010). "A subsequently Spearman's rank correlation test showed there was a positive correlation between the level of CXCR4 mRNA and that of TNF-α in 34 primary gastric cancers." (PMID 20699000, 2010). "There was another obvious upregulation of CXCR4 expression in cancer cells after they were co-cultured with macrophage, an alternative source of TNF-α in gastric cancer microenvironment." (PMID 20699000, 2010). "The overall findings led to our conclusion that TNF-α, with itself involved in the metastasis of gastric cancer, upregulates CXCR4 expression." (PMID 20699000, 2010). "Spearman's rank correlation test further verified a positive correlation of CXCR4 expression with TNF-α in these 34 gastric cancers (P < 0.01)." (PMID 20699000, 2010). "Although these findings have not been fully reproduced in humans, several papers suggest an indirect connection between cigarette smoking and TNF gene in the etiology of gastric cancer." (PMID 19615068, 2009). "In this study we determined the effect of silibinin on TNF-α-induced MMP-9 expression in gastric cancer cell lines." (PMID 19924065, 2009).
gastric cancer (continued). "Although, to our knowledge, this is the first study to report an interaction between the TNF gene and cigarette smoking on gastric cancer development, our study had several limitations." (PMID 19615068, 2009). "The present study investigated the bioactivities of GX1, as well as its potential ability to cooperate with recombinant mutant human tumor necrosis factor alpha (rmhTNFα), in gastric cancer therapy." (PMID 19740430, 2009). "In conclusion, we determined the effect of silibinin on TNF-α-induced MMP-9 expression in gastric cancer cells." (PMID 19924065, 2009). "Taken together, we suggest that silibinin down-regulates TNF-α-induced MMP-9 expression through inhibition of the MEK/ERK pathway in gastric cancer cells." (PMID 19924065, 2009). "All haplotype-pairs that contained TCT or CCC of TNF-α-1031 T/C, TNF-α-863 C/A, and TNF-α-857 C/T were associated with a significantly higher risk for gastric cancer only among smokers." (PMID 19615068, 2009). "An upregulation of MnSOD mRNA in gastric carcinoma was demonstrated, which provided a protective mechanism from the cell toxicity of tumor necrosis factor alpha from ROS." (PMID 16859522, 2006). "Moreover, our results provide a rationale for exploring therapeutic interventions targeting TNF-α in gastric cancer." (PMID 40299527, 2025). "A study on gastric cancer cell proliferation inhibition has stated that the Tumor necrosis signaling pathway (TNFα) played a major role in cell proliferation and targeting that could have better effects on cancer prognosis." (PMID 41186627, 2025). "For example, a composite score combining TNF-α, CA19-9, and perhaps IL-6 (another cytokine tied to gastric cancer prognosis) might better identify high-risk patients than any single marker." (PMID 40299527, 2025). "This study aimed to determine whether elevated TNF-α correlates with key tumor markers and disease stage in gastric cancer." (PMID 40299527, 2025). "In summary, further exploration of TNF-α—from its prognostic value to its potential as a treatment target—is warranted to determine how this multifaceted cytokine can be leveraged to improve gastric cancer outcomes." (PMID 40299527, 2025). "Finally, our study raises considerations for therapeutic interventions targeting TNF-α in gastric cancer." (PMID 40299527, 2025). "This suggests that gastric cancer-related TNF-α elevations may be driven more by localized tumor biology than by systemic acute-phase responses." (PMID 40299527, 2025). "The model R2 was 0.36 (adjusted R2 = 0.30), indicating that roughly one-third of the variability in TNF-α concentrations in gastric cancer patients could be accounted for by this set of clinical and laboratory factors." (PMID 40299527, 2025). "Gastric cancer cells secrete TNF-α to induce macrophages to release CXCL1 and CXCL5." (PMID 41583453, 2025). "A study of postoperative ENN intervention in patients with gastric cancer revealed that the serum levels of IL-6 and tumor necrosis factor-alpha (TNF-α) were significantly lower in the intervention group than in the control group, resulting in a lower degree of inflammation." (PMID 41393952, 2025). "Gastric cancer cells secrete TNF-α to induce release of CXCL1 and CXCL5 from macrophages." (PMID 41583453, 2025). "Furthermore, the use of gastric cancer exosomal THBS1 to enhance production of IFN-γ, TNF-α, perforin, and granzyme B in vitro, to ultimately elevate the killing of gastric cancer cells by Vδ2 T cells in vivo, has yielded successful preclinical trials." (PMID 40148988, 2025). "Thus, in the context of untreated gastric cancer patients, the balance appears to tip towards TNF-α being a facilitator of tumor progression." (PMID 40299527, 2025). "The roles that such cytokines, such as IL-2, TNF-α, and IFNs, could play would prove to be of significant importance in the suppression of gastric cancers." (PMID 40309351, 2025).
gastric cancer (continued). "Recognizing the role of TNF-α may help clinicians better stratify patients and develop more personalized, targeted management strategies for gastric cancer." (PMID 40299527, 2025). "Among TNFs, TNF-alpha is mainly involved in the early stages of gastric cancer." (PMID 38612999, 2024). "Taken together, these results demonstrate that the TNFα/NF-κB/HIF-1α pathway may contribute to CD204+ M2-like TAMs-dependent induction of miR-210 expression in gastric cancer cells." (PMID 38175202, 2024). "As the known pro-inflammatory cytokines inducing gastric cancer, IL-1β and TNF-α mediate H. pylori to initiate a large number of neutrophils and lymphoid cells to infiltrate gastric mucosa, highly polarized to Th1 cytokine response, leading to gastric mucosal injury and disease." (PMID 38774627, 2024). "Moreover, the inflammatory cascade initiated by gastric cancer surgery leads to a marked escalation in the levels of interleukin-6 (IL-6) and tumor necrosis factor-alpha (TNF-α), concurrent with a diminution in the expression of immunoregulatory cytokines." (PMID 39925886, 2024). "This is consistent with the results of previous studies that added GLP that 400 mg/kg GLP reduced serum levels of IL-1β and IL-6 in diabetic rats, and 800 mg/kg GLP reduced serum IL-6 and TNF-α levels and increased serum IL-2, IL-4, and IL-10 levels in rats with gastric cancer." (PMID 39457856, 2024). "TNF-α is known to be related to angiogenesis, progression, and metastasis in gastric cancer." (PMID 38444674, 2024). "Compared with those in the naloxone group, the expression levels of TLR4 (P < 0.05) in gastric cancer tissue in the naloxone group were greater; however, the expression levels of IL-6 (P < 0.01) and TNF-α (P < 0.01) in the naloxone group were greater than those in the nonnaloxone group." (PMID 38720250, 2024). "Loss of AQP3 might lead to reduced expression of inflammatory factors like IL-6 and TNF-α, and AQP3 inhibition could decrease the production of IL-6, IL-1β, and TNF-α, impairing intestinal bacteria clearance and contributing to gastric cancer progression." (PMID 39060229, 2024). "TNF is known to enhance inflammatory responses in gastric cancer." (PMID 38612999, 2024). "In addition, the effects of hepatoma-derived growth factor (HDGF) and tumor necrosis factor (TNFα) on the growth and invasion activity of H. pylori-infected gastric cancer organoids were examined." (PMID 37047540, 2023). "Thus, we propose that HDGF and TNFα are independent signals for development of H. pylori-infected gastric cancer." (PMID 37047540, 2023). "During gastric cancer surgery, EA combined with GA could also preserve innate tumor immunity and mitigate stress responses with a reduced plasma concentration of TNF-α compared with GA alone." (PMID 36765695, 2023). "In addition, it was reported that TNFα growth factor secreted from H. pylori infected gastric cancer cells was the upstream target factor of HDGF." (PMID 37047540, 2023). "It is suggested that γ-T3 may induce apoptosis in gastric cancer cells through TNF signaling pathway." (PMID 37055846, 2023). "Systemic lidocaine was also reported to improve postoperative recovery, alleviate inflammation and immunosuppression with a decrease in plasma TNF-α, and accelerate the return of bowel function in patients with gastric cancer undergoing laparoscopic radical gastrectomies." (PMID 36765695, 2023). "We found that the volatile components of R. rubescens could inhibit the activity of gastric cancer cells, possibly by regulating the levels of TNF, IL1B, MPP9 and PTGS2." (PMID 36200190, 2022). "Moreover, we screened lncRNAs related to the pathogenesis of gastric cancer and tried to investigate the effect of the H19/miR-204-5p/NF-κB axis in TP/TNF-α–induced apoptosis in gastric carcinoma." (PMID 36110523, 2022).
gastric cancer (continued). "In gastric cancer, the NF-κB signalling pathway could be activated after helicobacter pylori infection, which upregulates the expression of IL-1, IL-6, TNF-α, and endothelial growth factor, thereby activating the inflammasome and triggering cell pyroptosis." (PMID 36039017, 2022). "As H19 was reported to be the upstream member of the NF-κB pathway upon TNF-α stimulation, we speculated that H19 might play an essential role in TP/TNF-α–induced apoptosis in gastric cancer cells." (PMID 36110523, 2022). "In addition, the mechanism via which TNF-α-induced integrin αV promotes the metastasis of gastric cancer cells was verified." (PMID 36613819, 2022). "In addition, SMAD7 sensitizes breast and gastric cancer cells to TNF-induced apoptosis through down-regulation of the NFκB signaling pathway." (PMID 35917315, 2022). "This study was designed to explore whether TP increased the sensitivity of gastric cancer cells to the TNF-α stimulation and tried to find the mechanisms behind it." (PMID 36110523, 2022). "However, the mechanism behind TP–induced inhibition of NF-κB–mediated FLIP expression leading to an increase in gastric cancer cell sensitivity to TNF-α stimulation remained unclear." (PMID 36110523, 2022). "In order to have a more comprehensive understanding of the association of perioperative inflammatory states with long-term outcomes, the nonlinear association between the serum IL6_0 and TNFα_0 levels with survival in patients with gastric cancer was explored." (PMID 35859928, 2022). "For example, TGF-β and TNFα work in concert to activate apoptosis in gastric cancer cell." (PMID 35845961, 2022). "Recent studies show that serum concentrations of TNF alpha and CEA may be associated with gastric cancer and the pathogenesis of the gastrointestinal disease." (PMID 35186129, 2022). "Moreover, the serum IL-6 and TNFα levels were decreased, and the serum IL-2, IL-4 and IL-10 levels were increased in gastric cancer mice after tea polysaccharides treatment." (PMID 36505461, 2022). "Our findings indicate that the volatile oil of R. rubescens may promote the apoptosis of gastric cancer cells by inhibiting the expression of TNF, IL1B, MPP9, and PTGS2." (PMID 36200190, 2022). "In this study, we explored whether TNF-α enhanced the antitumor effect of TP against gastric carcinoma." (PMID 36110523, 2022). "In MNNG gastric cancer rat model, administration of 50, 100 or 150 mg/kg body weight of lycopene caused an increment in antioxidant enzymes as expected (SOD, CAT, GSH-Px) and increment in cytokines (IL-2, IL-4, IL-10, TNF-α) and antibodies (IgG, IgA, IgM)." (PMID 34202203, 2021). "In addition, PD-L1 expression induced by TNFα was also proved in gastric cancer, where mast cell infiltration was directly related to its progression and reduced overall survival." (PMID 33540543, 2021). "Overexpression of Notch-1 prevents gastric cancer cells from undergoing TNFα-mediated apoptosis." (PMID 33714199, 2021). "TNF-α -238G>A (rs361525) polymorphism was associated with the increased risk of gastric cancer in Chinese population, not in Caucasians 22,23 and was significantly associated with a high risk of gastritis in an African population." (PMID 34104107, 2021). "Notably, gastric cancer-derived TNFα induces PD-L1 expression of intratumoral mast cells via NF-κB signaling that inhibits T cell activity, further supporting its role as a tumor-promoting factor." (PMID 33406733, 2021). "In relation to gastric cancer, interleukin-6, 8, 10, 17A, TNF, and IFN-γ may have pro-tumour properties, although interleukin-10, TNF, and IFN-γ may have anti-tumour effects." (PMID 34944729, 2021). "Association between tumor-associated neutrophils (TANs) and metastases is apparently caused by the release of IL-1β, IL-6, IL-8, IL-17, and TNF-α, which induce the EMT process in gastric cancer cells by activation of cell signaling pathways such as JAK2/STAT3 and ERK1/2." (PMID 34503571, 2021).